STK11 (serine/threonine kinase 11)
Diseases named in the same sentence as STK11 in open-access papers (continued):
Sharing a sentence is not in itself a finding about the gene and the disease.
lung cancer (continued). "At first sight, these later studies suggested that the relatively limited effect of vistusertib in STK11 deficient/KRAS mutant lung cancer might have been predicted." (PMID 40069402, 2025). "However, GLS inhibition was found to impair CD8 + T-cell activation in STK11-/LKB1-deficient lung cancer, and the use of CB-839 to inhibit CD8 + T-cell expansion negatively impacted tumor therapy." (PMID 40598593, 2025). "The frequency of STK11 mutations in lung cancer varies from 5% to 30%." (PMID 40591555, 2025). "KRAS-mutant lung cancers are distinguished by recurrent loss of the tumor suppressor STK11/LKB1." (PMID 40316540, 2025). "Considering that STK11 mutation occurs in around 17% of all cases of lung cancer, such an approach could potentially improve patients' quality for the type of cancer with the highest mortality rates worldwide." (PMID 39955067, 2025). "Similarly, the combination of CB‐839 with PD‐1 inhibition demonstrates better therapeutic outcomes in Kras‐mutant STK11‐/Lkb1‐deficient mouse models of lung cancer by restoring CD8+ T cell function and improving the TME." (PMID 40959206, 2025). "Finally, BMP2 expression is correlated with metastatic burden and STK11 loss in lung cancer and mediates activation of SMAD transcription factors, which are known YAP1 binding partners." (PMID 37968341, 2024). "Loss of STK11 function was identified as a potential feature of malignant tumors in a variety of malignancies, such as cervical cancer, meningiomas, cholangiocarcinoma and lung cancer." (PMID 38736875, 2024). "Mutations in STK11 in lung cancer are truncating and truncation with loss of function." (PMID 38704802, 2024). "However, a different study revealed that combining CB839 with anti-PD-1 treatment inhibited the clonal expansion and activation of CD8 + T cells in KEAP1 and STK11 double-mutant lung cancer, resulting in a loss of therapeutic benefit." (PMID 38413563, 2024). "Additionally, we provide a review of recent advancements in research related to STK11 mutations in lung cancer as reported in the literature." (PMID 39717770, 2024). "Our analysis suggests that ADCs targeting MSLN may be particularly beneficial in lung cancer patients harboring dual mutations in STK11 and KEAP1 genes." (PMID 39186767, 2024). "SMARCB1 has been noted in STK11 deficient de-differentiated lung cancer." (PMID 39125735, 2024). "KEAP1 and LKB1 (STK11) mutations occur in approximately 20% of lung carcinomas." (PMID 38966170, 2024). "Thus, it remains practical to test our strategy in the future treatment of STK11-deficient lung cancer in the clinic." (PMID 37051524, 2023). "Additionally, in patients with lung cancer with STK11 mutations, high expression of CTGF has been correlated with better survival." (PMID 37381723, 2023). "STK11/LKB1 inactivation is common in KRAS-mutated lung cancer." (PMID 37670322, 2023). "STK11/LKB1 mutations were linked to resistance of PD-1 blockade in KRAS-mutant lung cancer." (PMID 36874015, 2023). "However, some evidence emphasizes that glutamate is also essential for the development and activation of effector T cells to exert anti-tumor function in STK11-/Lkb1-deficient lung cancer." (PMID 37215113, 2023). "STK11/LKB1 is a tumor suppressor commonly mutated in lung cancer and involved in the mTOR pathway." (PMID 35326552, 2022). "Furthermore, in a pooled analysis of the OAK and POPLAR studies, STK11/LKB1-mutated lung cancer patients had relatively worse OS than wild-type patients receiving atezolizumab." (PMID 35407463, 2022). "However, the presence of a phosphatase and tensin homolog (PTEN) or a serine/threonine kinase 11 (STK11) mutation was correlated with early progression in nonsmall cell lung cancer (NSCLC) patients receiving anti PD-1 IO." (PMID 35406441, 2022).
lung cancer (continued). "We first asked whether metformin can enhance T-cell mediated killing of lung cancer cells with STK11 mutation." (PMID 35281267, 2022). "The previous study has demonstrated that STK11 is a tumor suppressor and its loss-of-function mutation is involved in the morphological change from adenocarcinoma to squamous cell carcinoma, which further promotes lung cancer metastasis." (PMID 34795255, 2021). "Interestingly, the STK11 mutation, even though more enriched in the bone metastasis, are found to be the most abundant variant in the brain metastatic samples of lung cancer harboring the aberration of PI3K pathway (n = 146)." (PMID 34795255, 2021). "In contrast, other studies reported that lung cancer patients with STK11 mutated tumors could respond to ICIs." (PMID 33572782, 2021). "Furthermore, we observed that breast cancer metastases at any site that harbor mutations in KEAP1, KRAS, and STK11, a triplet commonly associated with lung cancer, genomically resemble lung tumors (100% vs. 18%, p = 2e-8, n = 13)." (PMID 32374727, 2020). "All together our results show that STK11ex1-2 mutations delineate an aggressive subtype of lung cancer for which a targeted treatment through STK11 inhibition might offer new opportunities." (PMID 26625312, 2017). "More recently, studies have suggested that the prognostic impact of KRAS mutation could be related to the presence of concurrent mutations such as STK11 that could define an aggressive subtype of lung cancer." (PMID 28445990, 2017). "However, glutaminase inhibition in specific tumor contexts, such as in STK11/LKB1-deficient lung cancer, may impair CD8+ T cell activation by limiting the expansion of T cell receptor clonotypes, a critical component for robust antitumor immunity." (PMID 39941865, 2025). "Notably, loss of Stk11/Lkb1 promotes SCC development in mouse lung cancer models." (PMID 40600748, 2025). "There are few reports about TTC39C (tetratricopeptide repeat domain containing 39c), which may be related to muscle cell differentiation through the MAP kinase and hedgehog signaling pathways and may be a new sensitive and specific gene expression marker in lung cancer harboring STK11 mutations." (PMID 35988113, 2022). "Therefore, we aim to study whether metformin can enhance T cell-mediated killing of STK11 mutant lung cancer and the underlying mechanisms." (PMID 35281267, 2022). "Thus, loss of STK11 in lung cancer cells may lead to enhanced sensitivity to palbociclib, demonstrating an STK11-loss evoked enhanced-dependency of cells on CDK4." (PMID 28205554, 2017). "However, it should be cautioned that due to mutational heterogeneity of STK11 and the relatively high concentrations of palbociclib used to observe the drug response in lung cancer cells, future studies will be needed to probe the molecular basis for STK11-directed therapeutic strategies." (PMID 28205554, 2017). "Thus, it is hypothesized that loss of STK11 in lung cancer may lead to enhanced dependency on upregulated CDK4." (PMID 28205554, 2017). "We retrospectively reviewed 1,068 primary lung cancer cases from 2018 to 2022, identifying 14 STK11-mutant lung adenocarcinomas." (PMID 41549133, 2026). "We also examined the requirement for STK11, a tumor suppressor and metabolic regulator frequently co-mutated with KRAS in lung cancer." (PMID 41892297, 2026). "Knockdown of PER1 decreases cell growth, proliferation, and invasion in LKB1-deficient models, which suggests that PER1 has an oncogenic role in STK11-mutant lung cancer." (PMID 40715535, 2025).
lung cancer (continued). "Intriguingly, our targeted investigation indicates that tipifarnib treatment or silencing of the farnesylation substrate PTP4A1 in STK11-mutant lung cancer cells results in inhibition of proliferation as well as impaired tonic interferon signaling." (PMID 39995872, 2025). "Analysis of an additional immunotherapy cohort, the MSK lung cancer cohort, corroborated our findings, demonstrating that mutations in KEAP1 or STK11 were linked to unfavorable outcomes, as evidenced by significantly poorer OS." (PMID 41378285, 2025). "While studying the response of KRAS-mutant lung cancer models to KRASG12C or MEK inhibitors combined with BH3 mimetics, we unexpectedly observed an association between the presence of STK11 mutations and dependence on MCL-1." (PMID 40316540, 2025). "To further explore the association between LKB1 and PER1 in lung cancer we used publicly available human lung cancer datasets to investigate how STK11 mutation status related to PER1 expression in lung adenocarcinoma." (PMID 40715535, 2025). "Some studies show that ENO3 has over expression and selective anticancer effect in STK11 Mutant Lung Cancers." (PMID 40464853, 2025). "The reason for this stems from the differences in both response to FTIs and differences in ferroptosis defense systems where STK11/KEAP1-mutant lung cancer harbors very effective anti-ferroptosis systems through SLC7A11/GPX4, AIFM2, and AKR1C." (PMID 39995872, 2025). "STK11 and KEAP1 co-mutations with KRAS are primarily observed in lung cancer, as these two genes are rarely mutated in other cancers with high KRAS mutation rates." (PMID 40611261, 2025). "Further confirming the dependence of AIFM2 expression on STK11 and KEAP1 mutations, significantly higher levels of AIFM2 at both protein and mRNA levels were seen in lung cancer samples with STK11/KEAP1 mutations." (PMID 39995872, 2025). "Ablation of STK11/LKB1 in a KRAS-driven lung cancer mouse model has led to the recruitment and accumulation of neutrophils to suppress T-cell function." (PMID 41254689, 2025). "Serine/threonine kinase 11 (STK11) acts as a tumor-inhibiting factor in NSCLC to inhibit lung cancer progression through regulation of cell metabolism and proliferation." (PMID 40296912, 2025). "Our analysis also provides indications that such combination therapy would be less effective in STK11-/KEAP1-mutated lung cancer and lung cancer of neuroendocrine lineage." (PMID 39995872, 2025). "We also sought to determine the impact of PER1 knockdown in the STK11-mutant A549 human lung cancer cell line." (PMID 40715535, 2025). "Studies have found that metformin can potentially target STK11 mutant lung cancer alone or in combination with conventional chemo/radiotherapy." (PMID 39308524, 2024). "Inactivation of STK11 in lung cancer appears to result in an immunologically cold tumor microenvironment, with reduced T cell infiltration." (PMID 38183584, 2024). "In lung cancer, STK11 knockdown has been reported to increase cell motility and invasiveness and influence many epithelial–mesenchymal transition (EMT) pathway marker proteins, such as ZEB1 and E-cadherin." (PMID 38461159, 2024). "In patients with lung cancer, we demonstrate that KRAS mutations increase tumor immunogenicity; however, KRAS/STK11 co-mutated patients display an immune-excluded phenotype." (PMID 39113608, 2024).
lung cancer (continued). "A study in which WES of primary lung–BrM pairs was carried out showed that BrMs exhibited higher somatic variants and chromosomal alterations than primary lung cancers, particularly in genes associated with lung cancer (e.g., KRAS, ROS1, and STK11)." (PMID 39593114, 2024). "For example, STK11 is a tumor suppressor gene that has an incidence rate of more than 10% in lung cancer and is extremely insensitive to immunotherapy." (PMID 39655075, 2024). "Recent studies have identified concurrent mutations in STK11 and KEAP1 that appear to protect against ferroptosis and promote SCD1 dependence in lung cancer." (PMID 38383297, 2024). "STK11 was targeted to create a pig model of lung cancer that shows evidence of inflammation; however, more work is required to fully develop the model." (PMID 37626695, 2023). "Inactivating mutations of the bona fide TSG STK11 (i.e., LKB1; serine/threonine kinase 11) are common in lung cancer, modulate differentiation and metastasis in vivo, and have been observed more frequently patients with smoking history." (PMID 37922356, 2023). "SCD1 inhibition induces ferroptosis in STK11/KEAP1-comutated lung cancer cells and blocks tumor growth." (PMID 37047797, 2023). "Lung cancer cells with STK11/LKB1 displayed various aberrancies such as improper Golgi positioning, lamellipodia formation, and morphology." (PMID 35165542, 2022). "Future clinical studies are required to further investigate the clinical benefits of metformin combined with PD-1 inhibitors in STK11 mutant lung cancer." (PMID 35281267, 2022). "Analysis of IMPOWER 150 also presented that, for the subgroup of patients with KRAS-mutant lung cancer carrying STK11 and/or Keap1 simultaneously, Atezolizumab combined with Bevacizumab and chemotherapy is an effective first-line treatment." (PMID 35887766, 2022). "In conclusion, the current study demonstrated that metformin overcomes primary resistance to PD-1 inhibitor in STK11 mutant lung cancer." (PMID 35281267, 2022). "Taken together, these results suggest that metformin enhanced T cell-mediated killing of STK11 mutant lung cancer cells in vitro." (PMID 35281267, 2022). "Although STK11/LKB1 mutant lung cancers carry an unfavorable prognosis, the administration of different chemotherapeutic agents that target mTOR, glutaminase, and PD-L1 has shown to increase survival in NSCLC patients." (PMID 35165542, 2022). "Clinically, Kras-mutant LUAD is dominated in three robust subsets of molecular lung cancer classifications, among which inactivation of the liver kinase B1 [Lkb1; or named as Serine/threonine kinase 11 (Stk11)] is the most frequently co-occurring events." (PMID 36358651, 2022).
lung cancer (continued). "STK11 and KEAP1 comutations have been associated with worse outcomes in patients with KRAS-mutant lung cancer treated with an ICI." (PMID 36426286, 2022). "A novel circRNA (circHIPK3) increases STAT3 expression by inhibiting miR-124-3p in STK11 mutant lung cancer cells." (PMID 36338714, 2022). "In the current study, we reported that metformin enhanced T cell-mediated killing and PD-1 inhibitor efficacy in STK11 mutant lung cancer." (PMID 35281267, 2022). "The current study provided a new approach, the combination of metformin and PD-1 inhibitor, to treat STK11 mutant lung cancer." (PMID 35281267, 2022). "We note that evidence from mouse models has implicated Lkb1 (STK11) loss as a key event in enabling transition from lung adenocarcinoma to lung SCC; a transition that has been linked to drug resistance in lung cancer patients." (PMID 36207323, 2022). "For example, secondary mutations in tumor suppressors, such as STK11 and CDKN2A, contribute to the KRAS independency in lung cancer cell lines." (PMID 34680229, 2021). "Compared to the TCGA data, the Nanjing Lung Cancer Cohort (NJLCC) and CHOICE cohort of Chinese patients revealed higher rates of EGFR and RB1 mutations, and lower rates of KRAS, BRAF, and STK11 mutations, in adenocarcinoma patients." (PMID 34195081, 2021). "Those genes are frequently altered in different cancers, including AKT1, EGFR, KRAS, and STK11 in lung cancer and AKT1, BRCA2, ERBB2, and PIK3CA in Breast cancer." (PMID 34906079, 2021). "For example, previous researches reported that ENO3 was highly expressed in STK11 mutant lung cancer, colorectal cancer, and its ectopic expression correlated with a worse outcome of patients by bioinformatic analysis." (PMID 35004693, 2021). "In vitro studies showed that STK11 inactivation increased cell motility, invasiveness, and favored epithelial–mesenchymal transition in lung cancer cells, thus enhancing metastatic potential." (PMID 34831355, 2021). "In a similar manner, circHIPK3 modulates autophagy via MIR124-3p-STAT3-PRKAA/AMPKα signaling in STK11 mutant lung cancer cells." (PMID 34326381, 2021). "The difference of STK11 and PTEN mutations in lung cancer suggested a differential function of these key regulators of the mTOR pathway in lung cancer development." (PMID 33652656, 2021). "In pre-clinical models, inactivation of STK11/LKB1 leads to the progression of lung cancer with the acquisition of metastatic properties." (PMID 34831355, 2021). "In agreement with that, KRAS/STK11 double mutant lung cancers showed worse survival compared to only STK11 mutants: TTP of ~two months vs. five months, and overall survival of ~seven months vs 16 months." (PMID 34164344, 2021). "A knockdown of ENO3 expression exhibited a selective anticancer effect in STK11 mutant lung cancer cells." (PMID 34869590, 2021). "In KRAS-mutated lung cancer, there is a synergic effect of STK11/LKB1 and KEAP1 loss: STK11/LKB1 loss results in an increased level of ROS and high redox stress with an inability to maintain ATP levels." (PMID 34831355, 2021).